B3GALT1 (beta-1,3-galactosyltransferase 1)
Description:
Beta-1,3-galactosyltransferase that transfers galactose from UDP-alpha-D-galactose to substrates with a terminal beta-N-acetylglucosamine (beta-GlcNAc) residue. Involved in the biosynthesis of the carbohydrate moieties of glycolipids and glycoproteins. Inactive towards substrates with terminal alpha-N-acetylglucosamine (alpha-GlcNAc) or alpha-N-acetylgalactosamine (alpha-GalNAc) residues.
Synonyms: Beta3Gal-T1
Tractability: Antibody: UniProt predicts a signal peptide or a membrane-spanning region. PROTAC: its protein half-life has been measured.
Target class: Enzyme; Transferase
Gene: Protein-coding gene on chromosome 2 (167,293,001 to 167,874,045, forward strand). Ensembl gene ENSG00000172318.
Subcellular location: Golgi apparatus membrane
Pathways (Reactome):
Metabolism: Lewis blood group biosynthesis
Gene Ontology:
Molecular function: N-acetyl-beta-D-glucosaminide beta-(1,3)-galactosyltransferase activity; hexosyltransferase activity
Biological process: glucosylceramide metabolic process; oligosaccharide biosynthetic process; carbohydrate derivative metabolic process; glycoprotein biosynthetic process
Cellular component: Golgi membrane; membrane
Genetic constraint (gnomAD): Loss-of-function variants: 10 observed, 23.91 expected, observed/expected ratio (o/e) 0.42, 90% interval 0.26 to 0.71. The upper end of that interval is the gene's LOEUF score, 0.71, which puts it in group 2 of 6, group 1 being the genes least tolerant of losing a copy. Missense variants: 299 observed, 428.69 expected, observed/expected ratio (o/e) 0.7, 90% interval 0.63 to 0.77. Synonymous variants: 156 observed, 149.6 expected, observed/expected ratio (o/e) 1.04, 90% interval 0.92 to 1.19.
Homologues: Orthologues: chimpanzee B3GALT1 (100% identical), guinea pig B3GALT1 (100% identical), macaque B3GALT1 (100% identical), mouse B3galt1 (100% identical), rat B3galt1 (100% identical), pig B3GALT1 (99% identical), rabbit B3GALT1 (99% identical), tropical clawed frog b3galt1 (91% identical), zebrafish b3galt1a (77% identical), Drosophila melanogaster brn (25% identical), Caenorhabditis elegans bre-5 (20% identical), Caenorhabditis elegans F21C10.3 (10% identical), and 1 more. Paralogues in human: B3GALT2 (46% identical), B3GALT5 (36% identical), B3GALNT1 (33% identical), B3GNT2 (29% identical), B3GNT5 (29% identical), B3GNT6 (27% identical), B3GALT4 (27% identical), B3GNT3 (27% identical), B3GNT4 (26% identical), B3GALT9 (25% identical), B3GNT7 (25% identical), B3GNT9 (25% identical), and 3 more.
Diseases named in the same sentence as B3GALT1 in open-access papers:
B3GALT1 is named in the same sentence as 7 diseases in open-access papers, as found by Europe PMC text mining. Sharing a sentence is not in itself a finding about the gene and the disease. The quoted sentences say what the papers report.
prostatic cancer (3 papers, 2013 to 2025). "In this study, we observed higher levels of B3GALT1 in CC patients who present metastasis after treatment, corroborating the association observed in prostate cancer." (PMID 41149858, 2025). "On the other hand, higher expression of B3GALT1 results in higher levels of MUC1-associated Sialyl Lewis antigen, which is linked to the metastasis of prostate cancer cells." (PMID 41149858, 2025).
breast carcinoma (1 paper, 2025). "High levels of B3GALT1 have been shown to enhance CD8+ T cell infiltration and reduce immune evasion, suppressing breast cancer lung metastasis." (PMID 41149858, 2025).
cancer (2 papers, 2017 to 2022). A tumor composed of atypical neoplastic, often pleomorphic cells that invade other tissues. "The CASC19, AC090197.1, AC099850.3, AL033397.2, LINC00462, and B3GALT1-AS1were found to be upregulated in the high-risk group, indicating that all these markers were involved in the malignancy processes for KIRP sufferers and were cancer-promoting factors." (PMID 36104680, 2022). "SKOV3 displayed strong expression of B3GALT5 and very weak expression of B3GALT1 and B3GALT2, consistent with the meta-analysis of the Cancer Cell Line Encyclopedia (CCLE)." (PMID 28167527, 2017).
tumor (1 paper, 2025). "Conversely, the genes downregulated in the MYB-expressing epithelial clusters were predominantly tumor-suppressive transcriptional signatures, including OCM, IER2, JPH2, RYR3, MYH11and B3GALT1." (PMID 40950184, 2025).
B3GALT1 also shares sentences with these, for which no sentence is quoted: autism (1 paper); Colon cancers (1); depression (1).